TLR4 (toll like receptor 4)
Diseases named in the same sentence as TLR4 in open-access papers (continued):
Sharing a sentence is not in itself a finding about the gene and the disease.
epilepsy (continued). "In this context, the increased expression of TLR4 in astrocytes, but not in microglia, suggests TLR4’s role in seizure frequency in human epilepsy." (PMID 35859905, 2022). "Moreover, glial cell stimulation also triggers epilepsy, and this stimulation is mediated by HMGB1 through the TLR4/ NF-κB signaling pathway during seizures." (PMID 33921725, 2021). "Therefore, it is possible that the interaction of HMGB1 with TLR4 constitutes a potential link between ASD and epilepsy." (PMID 34198762, 2021). "In our study, we did not found significant association between the level of TLR4 upregulation in FCD lesions and disease duration of epilepsy or seizure frequency." (PMID 29382328, 2018). "- Inhibiting the HMGB1/RAGE/TLR4 signaling axis could be a novel therapeutic strategy against several HMGB1 mediated conditions like TBI, neuroinflammation, epilepsy and cognitive dysfunction." (PMID 30271319, 2018). "Investigation on post-surgery patients with intractable epilepsy revealed increased levels of HMGB1, TLR4, RAGE, NF-κB, p65 and inducible nitric oxide synthase (iNOS) in the brain of the epilepsy group as well as increased levels of IL-1, IL-6, TNF-α, TGF-β, and IL-10 in epilepsy patients." (PMID 30271319, 2018). "Glial cells activation has been reported to serve an important role in the development of epilepsy and HMGB1 may mediate microglial activation via the TLR4/NF-κB signaling pathway during seizures." (PMID 30271319, 2018). "Pharmacological interventions targeting HMGB1, TLR4, RAGE, and NF-κB may be effective for drug-resistant epilepsy in the future." (PMID 26485677, 2015). "Animal models of acute and chronic seizures have shown that HMGB-1 receptors are expressed after experimental seizures and HMGB-1/Toll-like receptor-4 (TLR4) signaling plays a role in generating and perpetuating seizures and might be targeted to attain anticonvulsant effects in epilepsies." (PMID 37583518, 2023). "At the tissue level, the downregulation of the TLR4/NF-κB inflammatory pathway in epilepsy inhibited microglial activation and CD68 expression, inhibited hyperphagocytosis, inhibited the occurrence and exacerbation of epilepsy, and thus improved cognitive and emotional behavior after epilepsy." (PMID 35493845, 2022). "However, the TLR4/NF-κB inflammatory signaling pathway has not been widely studied in epilepsy, and the role of neuroinflammation in epilepsy has gradually received attention." (PMID 35493845, 2022). "Overexpression of miR-636 inhibiting IL1R1 expression could markedly downregulate the TLR4 signalling pathway not just in CF but also in other diseases, such as epilepsy, in which inactivation of the IL1R1/TLR4 pathway is implicated." (PMID 31803183, 2019). "TLR4 agonists, LPS and MPL, can attenuate seizure severity in pilocarpine-induced rats with temporal lobe epilepsy, and pentoxifylline may represent a promising drug to inhibit epilepsy progression by targeting the HMGB1/TLR4/RAGE signaling pathway in pentylenetetrazol (PTZ)-kindling rats." (PMID 35837232, 2022). "However, the involvement of TLR4 signaling in epilepsy has not been fully elucidated." (PMID 35647304, 2022). "However, TLR4 expression was significantly higher in epilepsy tissues compared to LGG (P<0.05), and not significantly different between epilepsy and HGG." (PMID 40809181, 2025).
ovarian carcinoma (89 papers, 2010 to 2025). A malignant neoplasm originating from the surface ovarian epithelium. "Research indicates that increased expressions of TLR4 and MyD88 are associated with diminished overall survival in ovarian cancer patients." (PMID 39390599, 2024). "Taken together, our results indicate that the Asp299Gly polymorphism in the TLR4 gene is associated with the development of ovarian cancer in women, especially in those with the HGSOC subtype." (PMID 36231099, 2022). "In ovarian cancer, LPS-induced activation of TLR4 can drive cellular proliferation, and TLR4 knockdowns demonstrate a loss of paclitaxel resistance." (PMID 33554122, 2021). "Expression of TLR4 combined with MyD88 in epithelial ovarian cancer turned out to be independent risk factor for shortened survival time." (PMID 30976817, 2019). "The aim of this study was therefore to examine the potential association between PAUF and TLR4 in ovarian cancer progression using ovarian cancer cell lines." (PMID 30111860, 2018). "Several studies have shown that the expression of TLR4 is associated with ovarian cancer progression, treatment resistance, and poor prognosis." (PMID 29228698, 2017). "TLR4/MD-2 complex-mediated MyD88-dependent activation of NF-κB and Akt promotes tumor-associated immunosuppression in epithelial ovarian cancer (EOC) via induction of immunesuppressive cytokines and indoleamine 2,3-dioxygenase (IDO)." (PMID 27118139, 2016). "The TLR4/MyD88 pathway has in recent years been proposed as a risk factor for carcinogenesis and chemoresistance in ovarian cancer." (PMID 24977712, 2014). "A study on the frequency of TLR polymorphisms found that the frequency of the TLR4 rs4986790 SNP was significantly elevated in patients with ovarian cancer, which may indicate its association with the development of ovarian cancer." (PMID 40727252, 2025). "Recent findings suggest that the TLR4 Asp299Gly polymorphism could be a genetic risk factor for the development of ovarian cancer." (PMID 38275400, 2024). "Additionally, it is worth mentioning that the TLR4 rs7869402 has been associated with reduced overall survival in ovarian cancer patients." (PMID 39026223, 2024). "A polymorphism in TLR4 was also found recently to be associated with increased ovarian cancer risk." (PMID 36765715, 2023). "Therefore, the present study suggests for the first time the existence of the TLR4-NF-κB-HIF-1α signaling pathway in ovarian cancer cells, which implicates an important association between the inflammatory pathway and hypoxia-response pathway." (PMID 35464826, 2022). "It was hypothesized that the presence of TLR4 variants may lead to the development of ovarian cancer." (PMID 24959291, 2014). "LINC00886 drives ovarian cancer progression and immune escape through themiR-423-5p/TLR4/Myd88/NF-κB/PD-L1 axis, establishing its potential as both a prognostic biomarker and therapeutic target." (PMID 40999508, 2025). "This was also the case in this study, where overexpression of TLR4 was a driver of malignant activity in ovarian cancer cells." (PMID 40999508, 2025). "Previous studies have shown that inhibiting the upregulated TLR4 expression in ovarian cancer can suppress its proliferation and invasion." (PMID 40999508, 2025). "For example, a previous study demonstrated that paclitaxel triggers ICD in ovarian cancer by activating cytotoxic mechanisms mediated via TLR4, IKK2, and SNARE proteins." (PMID 40918463, 2025). "In ovarian cancer, Paclitaxel’s interaction with TLR4 on TAMs activates NF-κB, shifting macrophages toward an M1 profile marked by increased production of pro-inflammatory cytokines such as TNFα and IL12." (PMID 40330466, 2025). "Transfection with miR-423-5p mimics significantly suppressed TLR4 mRNA expression in two ovarian cancer cell lines." (PMID 40999508, 2025). "In ovarian cancer tissues, a positive linear correlation was detected between TLR4 and LINC00886 (r = 0.624, P < 0.001)." (PMID 40999508, 2025).
ovarian carcinoma (continued). "Although TLR-4 is expressed in almost all ovarian epithelial cells, MyD88 seems to be expressed only in malignant ovarian tumors." (PMID 40404908, 2025). "In ovarian cancer, LPS induced the activation of TLR4, up-regulated osteopontin, and increased the malignant phenotype of ovarian cancer cells." (PMID 38463226, 2024). "lactis NCU-01 reverses cisplatin resistance in ovarian cancer by modulating the intestinal microbiota, inhibiting the TLR4/NF-κB signaling pathway and modulating the p38MAPK signaling pathway." (PMID 38947385, 2024). "In macrophages co-cultured with ovarian cancer, AS-IV suppresses the elevated levels of HmgB1 and TLR4, further supporting the notion that HmgB1 can promote M2 macrophages, whereas AS-IV has the opposite effect." (PMID 39064966, 2024). "The interaction between TLR4 and MyD88, the molecule considered to be the marker of stem cells in ovarian cancer, contributes to inflammation in the tumor environment and enhances its aggressive phenotype." (PMID 38275400, 2024). "Paclitaxel, but not carboplatin, was found to induce ICD through the release of HMGB1 and activation of TLR-4-dependent and -independent pathways in ovarian cancer." (PMID 35986757, 2023). "In ovarian cancer, high expression of TLR4 and MyD88 was found to predict poorer overall survival in patients with EOCs." (PMID 36765715, 2023). "DAB2 expression had a significant positive correlation with HA synthesis protein HAS2, HA receptor CD44 and co-receptor toll like receptor 4 (TLR4) in both ovarian cancer cell lines (CCLE) and patient tissues (TCGA: microarray and RNAsequencing data)." (PMID 37815603, 2023). "recently reported that TRAF3 interacts with the mitochondrial fusion protein mitofusin-1 (MFN1) in ovarian cancer cells, which is enhanced upon TLR4 signaling induced by Selene nanoparticles." (PMID 36776285, 2023). "Paclitaxel treatment resulted in the release of HMGB1 and activation of TLR-4-dependent and -independent pathways in ovarian cancer." (PMID 35366537, 2022). "Ovarian cancer tissues demonstrated the upregulated expression of TLR4 at mRNA and protein levels compared to normal ovaries." (PMID 36231099, 2022). "Paclitaxel, an antineoplastic agent, is used to treat ovarian cancer by reprogramming TAM into M1 phenotype via TLR4-signalling." (PMID 35600340, 2022). "A prominent example is an ovarian cancer where tissue-specific bacteria, L. lactis, seem to be in control of miR-200b and TLR-4 downregulation, which is connected to the progression of ovarian cancer." (PMID 36158660, 2022). "While there is a lack of information that relates IL-1α to paclitaxel, previous works have described that paclitaxel induces the upregulation of IL-6 in ovarian cancer cells through the TLR4–NF-κB cascade." (PMID 35163066, 2022). "TLR4 signaling pathway has been reported to play a crucial role in various cancers, including human oral squamous cell carcinoma, ovarian cancer and prostate cancer." (PMID 36224753, 2022). "Toll-like receptor 4 (TLR4), a member of the TLRs family, which is the indispensable receptor for lipopolysaccharide (LPS), is detected in a variety of tumors, including in ovarian malignant tumors." (PMID 35464826, 2022). "The functionality of LPS-induced inflammation is highlighted by the fact that the blockade of TLR4 reduces ovarian cancer proliferation and TLR4 activation promotes proliferation and induces drug resistance." (PMID 33794773, 2021). "Different disease models have shown melatonin repressing pro-oxidant TLR2- and TLR4-mediated signaling cascades in the inflammatory phenotypes of ovarian cancer and coronary artery disease." (PMID 34356384, 2021). "Of note, the role of TLR4 in ovarian cancer is well documented, and future studies should also investigate the possibility of asprosin binding to TLR4 as well in ovarian cells." (PMID 34386072, 2021).
ovarian carcinoma (continued). "Treatment of ovarian cancer cells with Lactobacillus lactis, a vaginal synbiont, modulates the expression of miR-21 and miR-200b, and, subsequently, TLR4 responsiveness of CAOV-4 cells." (PMID 33794773, 2021). "Additional evidence showed that ALKBH5 was highly expressed in ovarian cancer tissue, but decreased in cancerous cell lines, whose expression pattern is consistent with Toll-like receptor (TLR4)." (PMID 33611339, 2021). "Paclitaxel is used to treat ovarian cancer by polarizing M2 into M1 macrophages in a TLR4-dependent manner." (PMID 33680950, 2020). "The expression level of TLR4 was significantly higher in ovarian cancer tissue than in the normal tissue, but lower in ovarian cancer cell lines (P < .05)." (PMID 32329191, 2020). "This was investigated using siRNA knockdown of MAD2, TLR4 and MyD88 in two ovarian cancer cell lines, A2780 and SKOV-3 cells and overexpression of MyD88 in A2780 cells." (PMID 33370338, 2020). "In this study, we demonstrate a key link between senescence and inflammation and how this complex network involving the biomarkers MAD2, TLR4 and MyD88 drives paclitaxel resistance in ovarian cancer." (PMID 33370338, 2020). "Elevated expression levels of TLR4 or it’s adaptor protein MyD88 have been associated with reduced survival outcome in HGSOC patients, while therapeutic targeting of TLR4 has been shown to restore paclitaxel sensitivity in ovarian cancer cell models." (PMID 33370338, 2020). "In an ovarian cancer study, researchers found that TLR4 rs7869402 variation reduced the overall survival of ovarian cancer." (PMID 32351566, 2020). "Our group and others have previously demonstrated that TLR4, MyD88 and MAD2 play key roles in paclitaxel resistance in ovarian cancer and are associated with poor patient outcome." (PMID 33370338, 2020). "Taken together, TLR4 can create an inflammatory microenvironment for ovarian cancer cells through activating NF‐κB signalling pathway." (PMID 32329191, 2020). "To further explore the link between TLR4 and MAD2 we next analysed the expression of MAD2, TLR4 and MyD88 in 5 additional ovarian cancer cell lines; OVCAR-3, PEO1, OAW42, KURAMOCHI and 59M cells." (PMID 33370338, 2020). "TLR4 signaling is upregulated in numerous ovarian epithelial cancers, and the level of expression correlates with increased cancer progression and chemoresistance to paclitaxel." (PMID 30111860, 2018). "For example, the knockdown of MyD88 results in a failure of ovarian cancer cell proliferation and cytokine production in response to LPS, suggesting that TLR4-MyD88 cell signaling contributes to epithelial ovarian cancer growth." (PMID 29928275, 2018). "Recently, XIAP has been reported in the PTX-induced TLR4/MyD88-dependent signaling pathway in ovarian cancer." (PMID 29486738, 2018). "Galectin-3 can induce ovarian cancer cell survival and chemoresistance through activating TLR4 pathway." (PMID 29788922, 2018). "The correlation between expression of PAUF and TLR4 was assessed in epithelial ovarian cancer and precancerous lesions." (PMID 30111860, 2018). "PAUF and TLR4 expression was compared between specimens from chemosensitive (n = 147) and chemoresistant (n = 43) ovarian cancer." (PMID 30111860, 2018). "The effect of recombinant PAUF treatment was investigated in transfected SKOV3 and A2780 cells with silencing siRNAs of PAUF or/and TLR4 to confirm the role of PAUF on ovarian cancer cell proliferation." (PMID 30111860, 2018). "Expression of PAUF and TLR4 was analyzed in specimens from normal tissue (n = 72), benign tumor (n = 69), borderline tumor (n = 62), ovarian cancer (n = 205), and metastatic tissues (n = 52)." (PMID 30111860, 2018). "The poor outcome and chemoresistance of ovarian cancer patients with TLR4 overexpression in our study are consistent with those previous studies." (PMID 30111860, 2018).
ovarian carcinoma (continued). "To explore the association between TLR4 signal pathway and OPN, as well as the possible mechanism that OPN promoted the metastasis phenotype of ovarian cancer cells, we used RNAi to knockdown OPN in HO-8910PM cells." (PMID 29228698, 2017). "Taken together, our study demonstrates that OPN contributes to the ovarian cancer cell proliferation and metastasis, which is activated by TLR4 signaling pathway." (PMID 29228698, 2017). "Overall, the OPN expression in ovarian cancer cells is significantly up-regulated by the activation of TLR4 via LPS stimulation." (PMID 29228698, 2017). "In particular, TLR4 expression was reported to have key roles in development of some tumors including prostate or ovarian cancers." (PMID 28212583, 2017). "Taken together, activation of TLR4 signal pathway can enhance the proliferation and metastatic ability of ovarian cancer cells, which directly promotes a malignant metastatic phenotype." (PMID 29228698, 2017). "Similar findings were reported for TLR4 signaling and paclitaxel chemoresistance in ovarian cancer suggesting a putative role of TLR4 signaling in the development of chemoresistant cancer cells." (PMID 26863029, 2016). "Certainly, the role of TLR4/MD-2 complex for activation of MyD88/NF-κB signaling needs to be further studied in a variety of ovarian cancer cell lines of different phenotypes, and even in vivo study." (PMID 27118139, 2016). "Active TLR-4/MyD88 signalling was also found in epithelial ovarian cancer cells and influenced the drug response." (PMID 26881027, 2016). "The relationships between the expressions of TLR-4, MyD88, and NF-κB have been examined in epithelial ovarian cancer patients." (PMID 26881027, 2016). "The activation of TLR4/MyD88/NF-κB signaling enhances aggressive tumor phenotype with poorer clinical outcome in epithelial ovarian cancer patients." (PMID 27655682, 2016). "Specifically curcumin and quercetin as a ligand of MD-2 or TLR4 potently repress TLR4/MyD88/NF-кB signal pathway and inhibit immunosuppressive cytokine production, and suppress ovarian cancer cell metastasis." (PMID 27118139, 2016). "Previous studies have demonstrated that the activation of TLR4-MyD88 signaling favors tumor growth and chemoresistance in ovarian cancer." (PMID 27708225, 2016). "In the present study, cases of ovarian cancer were analyzed with regards to Asp299Gly and Thr399Ile of the TLR4 gene." (PMID 24959291, 2014). "The results suggested that the TLR4-MyD88 signaling negatively regulates ovarian cancer cell sensitivity to Pac." (PMID 24527095, 2014). "The current study investigated the effects of TLR4 in ovarian cancer, particularly in Pac chemotherapy." (PMID 24527095, 2014). "Cell proliferation and apoptosis were assessed in the cells transfected with scramble control and TLR4 shRNA to explore the possible functions of TLR4 in ovarian cancer cell growth." (PMID 24527095, 2014). "The present study investigated the effect of TLR4 ligation by Pac in MyD88-positive (MyD88+) and MyD88-negative (MyD88−) human ovarian cancer cell lines." (PMID 24527095, 2014). "In conclusion, the observations of the current study imply that Pac activates TLR4-MyD88 signaling, which increases ovarian cancer cell proliferation." (PMID 24527095, 2014). "The results of the present study support that MyD88 acts as a downstream factor and combines with TLR4 to increase the proliferation of ovarian cancer cells." (PMID 24527095, 2014). "In the present study, it was identified that Pac activates TLR4 signaling, which increases ovarian cancer cell proliferation." (PMID 24527095, 2014). "An RNA interference expression vector was specifically constructed to target TLR4 mRNA, which was stably transfected into the human ovarian cancer cell lines (SKOV3, OVCAR3, A2780 and 3AO)." (PMID 24527095, 2014).